RN7SL815P (RNA, 7SL, cytoplasmic 815, pseudogene)
Gene: Miscellaneous RNA gene on chromosome 3 (115,837,870 to 115,838,159, forward strand). Ensembl gene ENSG00000243359.
Homologues: Orthologues: chimpanzee Metazoa_SRP (99% identical), macaque Metazoa_SRP (93% identical). Paralogues in human: RN7SL1 (83% identical), RN7SL2 (83% identical), RN7SL220P (82% identical), RN7SL3 (82% identical), RN7SL113P (80% identical), RN7SL516P (80% identical), RN7SL788P (80% identical), RN7SL566P (80% identical), RN7SL712P (80% identical), RN7SL126P (80% identical), RN7SL709P (80% identical), RN7SL11P (79% identical), and 703 more.